FIBP (FGF1 intracellular binding protein)
Description:
May be involved in mitogenic function of FGF1. May mediate with IER2 FGF-signaling in the establishment of laterality in the embryo (By similarity).
Synonyms: FGFIBP; FIBP-1; TROFAS
Tractability: Antibody: UniProt places it where antibodies can reach, with medium confidence. PROTAC: ubiquitination databases record sites on it; its protein half-life has been measured.
Gene: Protein-coding gene on chromosome 11 (65,883,740 to 65,888,531, reverse strand). Ensembl gene ENSG00000172500.
Subcellular location: Nucleus; Endomembrane system
Subcellular location (Human Protein Atlas): Nuclear speckles
Gene Ontology:
Molecular function: fibroblast growth factor binding
Biological process: platelet aggregation; fibroblast growth factor receptor signaling pathway
Cellular component: membrane; nuclear speck; nucleus; mitochondrion; endomembrane system
Genetic constraint (gnomAD): Loss-of-function variants: 27 observed, 36.9 expected, observed/expected ratio (o/e) 0.73, 90% interval 0.54 to 1.01. The upper end of that interval is the gene's LOEUF score, 1.01, which puts it in group 4 of 6, group 1 being the genes least tolerant of losing a copy. Missense variants: 407 observed, 466.11 expected, observed/expected ratio (o/e) 0.87, 90% interval 0.8 to 0.95. Synonymous variants: 215 observed, 194.12 expected, observed/expected ratio (o/e) 1.11, 90% interval 0.99 to 1.24.
Homologues: Orthologues: chimpanzee FIBP (100% identical), macaque FIBP (100% identical), dog FIBP (98% identical), pig FIBP (98% identical), rat Fibp (98% identical), guinea pig FIBP (98% identical), mouse Fibp (97% identical), tropical clawed frog fibp (77% identical), zebrafish fibpa (73% identical), zebrafish fibpb (70% identical), Drosophila melanogaster Fibp (44% identical).
Diseases named in the same sentence as FIBP in open-access papers:
FIBP is named in the same sentence as 20 diseases in open-access papers, as found by Europe PMC text mining. Sharing a sentence is not in itself a finding about the gene and the disease. The quoted sentences say what the papers report.
breast carcinoma (2 papers, 2015 to 2018). "A previous study reported that FIBP-depleted breast cancer cells displayed impaired proliferation and decreased migration." (PMID 30275459, 2018). "For example, FIBP can bind to KIAA0528 and CDK5 to form a stable complex, which participates in breast cancer cell growth and migration." (PMID 30275459, 2018).
colorectal cancer (2 papers, 2018 to 2025). A primary or metastatic malignant neoplasm that affects the colon or rectum. "FIBP encodes the acidic fibroblast growth factor intracellular-binding protein, which plays several important roles such as mitogenesis, embryonic development, and colorectal cancer chemoresistance." (PMID 40427702, 2025).
Intellectual disability (2 papers, 2023 to 2024). "As recessive loss-of-function mutations in FIBP cause Thauvin–Robinet–Faivre syndrome, a congenital syndrome characterized by tall stature, intellectual disability and renal anomalies, the identified variant is unlikely relevant for the neuromyopathy phenotype in our family." (PMID 37070754, 2023).
acute myeloid leukemia (1 paper, 2023). Acute myeloid leukemia (AML) is a group of neoplasms arising from precursor cells committed to the myeloid cell-line differentiation. "FIBP expression was further compared in 70 GTEx normal samples and 173 TCGA acute myeloid leukemia samples." (PMID 37310595, 2023). "However, the role of FIBP in acute myeloid leukemia remains largely unknown." (PMID 37310595, 2023). "To date, the role of FIBP in acute myeloid leukemia has not been investigated." (PMID 37310595, 2023).
colon carcinoma (1 paper, 2023). "Studies have shown that FIBP increased tumorigenicity and was highly expressed in colon carcinoma." (PMID 37310595, 2023).
Crohn disease (1 paper, 2019). A gastrointestinal disorder characterized by chronic inflammation involving all layers of the intestinal wall, noncaseating granulomas affecting the intestinal wall and regional lymph nodes, and transmural fibrosis. "Another GWAS SNP rs568617, associated with Psoriasis and Crohn’s disease, resided in intron of the gene FIBP next to CTSW and was in high LD with the CTSW promoter SNP rs658524 (r2 = 0.99 to rs658524; r2 = 0.19 to rs3903072)." (PMID 31507631, 2019).
lung adenocarcinoma (1 paper, 2023). A carcinoma that arises from the lung and is characterized by the presence of malignant glandular epithelial cells. "Collectively, our data show that loss of FIBP enhances lung adenocarcinoma radiosensitivity in vitro and in vivo." (PMID 37564211, 2023). "Overexpression of STAT3 partially reversed the decrease in the mRNA and protein levels of EME1 in FIBP-deficient lung adenocarcinoma cells, indicating that FIBP controls the expression of EME1 in a STAT3-dependent manner." (PMID 37564211, 2023). "In this study, we show that FIBP protein expression in lung adenocarcinoma tissues is upregulated and associated with worse overall survival." (PMID 37564211, 2023). "Notably, loss of FIBP also led to decreased protein levels of EME1 in two different lung adenocarcinoma cell lines, whereas overpression of FIBP increased the expression of EME1." (PMID 37564211, 2023). "To determine whether EME1 is an effector of FIBP in lung adenocarcinoma, we transfected the EME1 plasmid into FIBP-deficient H1299 cells." (PMID 37564211, 2023). "Moreover, loss of FIBP led to enhanced radiosensitivity in lung adenocarcinoma cells, whereas overexpression of FIBP exhibits reverse effect." (PMID 37564211, 2023). "Functionally, we find that depletion of FIBP inhibits lung adenocarcinoma progression and radioresistance in vitro and in vivo." (PMID 37564211, 2023). "Our results not only elucidate the mechanism by which FIBP functions but also provide a novel promising target for lung adenocarcinoma radiotherapy." (PMID 37564211, 2023). "Here, we revealed that FIBP associates with STAT3 to stimulate its transcriptional activity, which consequently induces the expression of EME1, thereby driving lung adenocarcinoma radioresistance." (PMID 37564211, 2023). "To identify the downstream effector of FIBP in lung adenocarcinoma, we used RNA-seq to explore the transcription profiles of lung adenocarcinoma cells transfected with FIBP siRNAs." (PMID 37564211, 2023). "In this work, we report that FIBP is upregulated and contributes to lung adenocarcinoma progression and radioresistance in vitro and in vivo." (PMID 37564211, 2023). "We then quantified the protein level of FIBP in a human lung adenocarcinoma tissue microarray." (PMID 37564211, 2023). "Furthermore, we showed that the FIBP mRNA and protein levels were higher in lung adenocarcinoma cell lines than in the normal cell line HBE." (PMID 37564211, 2023). "Given that FIBP is upregulated in lung adenocarcinoma tissue, we hypothesized that FIBP may contribute to tumorigenesis." (PMID 37564211, 2023). "Indeed, we discovered that FIBP was upregulated and predicted worse outcomes in lung adenocarcinoma." (PMID 37564211, 2023). "Collectively, these data support the hypothesis that FIBP drives lung adenocarcinoma cell proliferation in vitro." (PMID 37564211, 2023). "Our data demonstrated that the observed effects induced by FIBP silencing were reversed at least partially by ectopic expression of EME1, implying that EME1 also participates in the biological function of lung adenocarcinoma." (PMID 37564211, 2023). "A clear endogenous interaction between FIBP and STAT3 was also observed in lung adenocarcinoma cells." (PMID 37564211, 2023). "In addition, we showed that FIBP is overexpressed in lung cancer and that high FIBP expression is correlated with worse survival, implying that FIBP may be a promising prognostic marker in lung adenocarcinoma." (PMID 37564211, 2023). "However, the function and mechanism of FIBP in lung adenocarcinoma are totally unknown." (PMID 37564211, 2023). "To explore the mRNA level of FIBP in lung adenocarcinoma, we first analyzed matched NSCLC samples in The Cancer Genome Atlas (TCGA) and GEO and found that the mRNA level of FIBP was increased in lung cancer tissues compared with normal tissues." (PMID 37564211, 2023).
lung adenocarcinoma (continued). "Taken together, these findings demonstrate that FIBP is a novel positive regulator of STAT3 and controls STAT3-dependent EME1 expression in lung adenocarcinoma." (PMID 37564211, 2023). "Thus, our results indicate that FIBP may function as an oncoprotein in lung adenocarcinoma." (PMID 37564211, 2023). "Accordingly, these results suggest that FIBP binds to STAT3 to enhance its transcriptional activity, thereby inducing EME1 expression in lung adenocarcinoma cells." (PMID 37564211, 2023). "In summary, our research illustrates that FIBP interacts with STAT3 to increase its phosphorylation, thereby enhancing its transcriptional activity and inducing the expression of its target gene EME1, which ultimately contributes to lung adenocarcinoma progression and radioresistance." (PMID 37564211, 2023). "Our work reveals that FIBP modulates the STAT3/EME1 axis to drive lung cancer progression and radioresistance, indicating that targeting FIBP may be a novel intervention strategy for lung adenocarcinoma radiotherapy." (PMID 37564211, 2023).
lung carcinoma (1 paper, 2023). "We further showed that overexpression of exogenous STAT3 reversed the decrease in EME1 expression in FIBP-deficient lung cancer cells, indicating that FIBP upregulates EME1 in a STAT3-dependent manner." (PMID 37564211, 2023). "Moreover, FIBP-deficient lung cancer cells showed increases in γ-H2AX foci formation and the Olive tail moment, and these increases were partially reversed by overexpression of EME1." (PMID 37564211, 2023). "Further functional studies clearly showed that knockdown of FIBP significantly suppressed tumorigenesis, supporting the oncogenic role of FIBP in lung cancer." (PMID 37564211, 2023). "The FIBP protein levels were increased in the lung cancer tissues compared with the paired adjacent lung tissues." (PMID 37564211, 2023). "Suppression of FIBP inhibited DNA damage repair and contributed to enhanced radiosensitivity in lung cancer cells." (PMID 37564211, 2023). "Downregulation of FIBP significantly reduced the growth and proliferation ability of lung cancer cells." (PMID 37564211, 2023). "Reconstitution of EME1 partially reversed the suppressive effects of FIBP knockdown on lung cancer cell growth and proliferation." (PMID 37564211, 2023). "Among these genes, EME1 exhibited the greatest downregulation in FIBP-depleted lung cancer cells." (PMID 37564211, 2023).
mastitis (1 paper, 2023). Inflammation of breast tissue during lactation or postpartum due to an obstructed duct or infection. "The FIBP binds fibroblast growth factor 1 (FGF1), which is involved in defense mechanisms against bacterial invasion in mastitis." (PMID 37685039, 2023).
non-small cell lung carcinoma (1 paper, 2023). A group of at least three distinct histological types of lung cancer, including non-small cell squamous cell carcinoma, adenocarcinoma, and large cell carcinoma. "In our work, we identified FIBP as a novel STAT3-interacting protein in non-small cell lung cancer." (PMID 37564211, 2023).
Thauvin-Robinet-Faivre syndrome (1 paper, 2025). "This case report expands the phenotypic spectrum of Thauvin-Robinet-Faivre syndrome (TROFAS, OMIM #617107), a rare autosomal recessive disorder caused by biallelic loss-of-function mutations in the FIBP gene." (PMID 40536757, 2025).
cancer (5 papers, 2018 to 2023). A tumor composed of atypical neoplastic, often pleomorphic cells that invade other tissues. "To further confirm this phenomenon in vivo, we generated FIBP knockdown cancer cell lines stably expressing FIBP-targeting shRNAs." (PMID 37564211, 2023). "FIBP knockout consistently promoted T cell-mediated cancer killing and significantly reduced tumor size." (PMID 37310595, 2023). "FIBP expression was explored in pan-cancer data from TCGA and GTEx." (PMID 37310595, 2023). "FIBP knockdown increased sensitization of chemoresistant cells and attenuated cancer stemness." (PMID 37310595, 2023). "In 168 tumors and single-cell expression data from 19 kinds of cancer, the high expression of the FIBP gene in T cells almost indicates the low match of the Tres model, which means that T cells with high expression of the FIBP gene are not regarded as a tumor-resilient T cell." (PMID 37240834, 2023). "Among these target genes, KLK9, WNT3A, FGF18, FIBP, SOX12, TGFBI, and NEDD9 have been reported to participate in the development of human cancers." (PMID 33344223, 2020).
tumor (3 papers, 2018 to 2023). "To investigate the effect of FIBP silencing on tumor growth in vivo, we established xenograft mouse models by injecting SW620 cells and HCT116-CSCs with/without FIBP knockdown into the left/right dorsal flank of mice, respectively." (PMID 30275459, 2018). "Consistently, FIBP knockdown significantly decreased xenograft tumor burden, as evidenced by reduced tumor weight and tumor size during the observation time of 5 weeks for both SW620 cells and HCT116-CSCs." (PMID 30275459, 2018). "Moreover, it was showed that FIBP was also highly expressed in skin carcinogenesis and was involved in tumor cell cycle processes by regulating the key downstream target cyclin D1." (PMID 37310595, 2023). "FIBP was reported to be highly expressed in multiple tumor types." (PMID 37310595, 2023). "A few previous studies have reported that FIBP is involved in tumor cell cycle processes." (PMID 30275459, 2018). "Mechanistically, we showed that FIBP bound to GSK3β, which inhibited phosphorylation of GSK3β at Tyr216 and activated β-catenin/TCF signaling to accelerate cell cycle and promote tumor growth." (PMID 30275459, 2018).
FIBP also shares sentences with these, for which no sentence is quoted: Adams-Oliver syndrome (1 paper); breast tumor (1); congenital myasthenic syndrome (1); cortical dysplasia (1); developmental delay (1); psoriasis (1); tetraplegia (1).